CRP (C-reactive protein)
Diseases named in the same sentence as CRP in open-access papers (continued):
Sharing a sentence is not in itself a finding about the gene and the disease.
infection (continued). "PTX3 differs structurally and functionally from short pentraxins such as C-reactive protein (CRP), being synthesized locally at sites of infection by monocytes, macrophages, endothelial, and epithelial cells." (PMID 41471254, 2025). "Normalization of infection-related biomarkers (WBC, NE%, PCT, CRP) was observed in 95.6% of patients in the cefepime group and 100% in the comparator group (P = 0.375)." (PMID 40606637, 2025). "After 6 weeks of treatment, the infection markers significantly decreased (WBC 6.28 × 109/L, ESR 45 mm/h, CRP 17.3 mg/L), and body temperature stabilized below 37.5°C; besides, follow-up MRI showed substantial absorption of the soft tissue fluid." (PMID 40725965, 2025). "Corroborative evidence of IPN in the form of increased serum biomarkers of infection, such as procalcitonin (PCT), C-reactive protein (CRP), and total leucocyte count (TLC), aids in decision-making in these cases." (PMID 40421342, 2025). "Despite the recognized roles of CRP and SAA1 in modulating immune responses during infection, the specific function of SAA1 in the early stage of S. pneumoniae infection remains poorly defined." (PMID 40572197, 2025). "CRP and PCT are sensitive indicators of infection severity in RMPP, and elevated CRP has previously been reported as a predictor of mucus plug formation in pediatric MPP." (PMID 41561092, 2025). "Preoperative levels of individual inflammatory markers predicted infection with the following AUCs and cut-off values: NLR, 0.704 (cut-off: 2.528); MLR, 0.608 (0.2317); CRP, 0.516 (4.125 mg/L); ESR, 0.533 (66.5 mm/h); and FIB, 0.552 (3.415 g/L)." (PMID 40011028, 2025). "C reactive protein (CRP) is produced by the liver in response to inflammation, infection and tissue injury and is routinely available in emergency departments." (PMID 41204018, 2025). "After 5 days of antibiotic treatment, the inflammatory markers—C-reactive protein (CRP) and procalcitonin (PCT)—returned to normal levels, indicating that the infection was under control." (PMID 41416084, 2025). "CRP increases more gradually than PCT, usually 24-48 hours after the onset of infection, making its initial diagnosis more restricted but valuable for detecting disease progression or remission." (PMID 41246697, 2025). "C-reactive protein (CRP), synthesized by hepatocytes in response to IL-6 and IL-1 signalling, is a key marker of inflammation, infection or tissue damage." (PMID 40894478, 2025). "Fourth-line therapy with amrubicin (40 mg/m2) rapidly resulted in consolidation and wall thickening in the right lower lobe, with almost normal infection-related marker values: WBC count of 12.2 × 109/L and CRP level of 1.68 mg/L." (PMID 40727278, 2025). "C-reactive protein (CRP) is a positive acute-phase reactant synthesized by the liver, and its level in the blood rises in response to inflammation and infection within hours." (PMID 41170250, 2025). "Considering the prevalence from the present study cohort of 65.2% for infections in ICU patients, the PPV and NPV were highest for ICIS, lower for PCT and lowest for CRP, using the best cutoff values from the present study." (PMID 40471473, 2025). "In our study, the metabolomic panel outperformed the traditional infection markers WCC, CRP, and procalcitonin." (PMID 41195955, 2025). "A recently published meta-analysis observed that persistently elevated serum CRP and PCT were good predictors of infection in ANP with a pooled AUC of 0.88 and 0.86 for CRP and PCT, respectively." (PMID 40421342, 2025). "C-reactive protein (CRP) serves as a highly sensitive inflammatory biomarker reflecting acute inflammatory conditions, such as trauma, infection, and infarction, while also providing valuable prognostic information." (PMID 40444244, 2025). "The EASL guidelines propose CRP ≥ 10 mg/L and PCT ≥ 0.49 ng/mL as cut-off values for the assessment of infection, but these recommendations are mainly based on older studies." (PMID 41354872, 2025).
infection (continued). "Blood tests revealed neutrophil-predominant leukocytosis, elevated C-reactive protein (CRP), and positive procalcitonin (PCT) levels, indicating infection." (PMID 40125132, 2025). "Despite growing evidence, the predictive accuracy of CRP and NLR for postoperative infections in GI surgery remains uncertain." (PMID 41018345, 2025). "The following outcomes were compared for changes between preoperative and last follow-up results: erythrocyte sedimentation rate, C-reactive protein, VAS scores, HSS scores, knee ROM, and infection cure rates." (PMID 40978848, 2025). "CRP and PCT are two commonly used biochemical markers for assessing the body’s inflammation and infection status." (PMID 40821637, 2025). "Inflammatory markers such as C-reactive protein (CRP), procalcitonin (PCT), and fibrinogen are routinely used to evaluate infection severity and therapeutic response." (PMID 41153844, 2025). "The authors of this study reported that although the overall diagnostic accuracy of D-dimer was similar to that of ESR and CRP, D-dimer had a higher sensitivity than CRP and ESR in infections resulting from low-virulence pathogens." (PMID 39203582, 2024). "Blood investigations on admission revealed elevated infection markers, with a white blood cell (WBC) count of 8.8 × 109/L (reference range: 4.0-11.0 × 109/L) and a C-reactive protein (CRP) level of 97 mg/L (reference range: <5 mg/L)." (PMID 39629288, 2024). "Laboratory investigations showed a normal complete blood count and C-reactive protein (CRP), ruling out significant infection or ongoing inflammation." (PMID 39781116, 2024). "The findings confirm that traditional inflammatory markers, such as CRP and PCT, alongside indices such as NLR and MPV, are valuable in assessing the severity of infections." (PMID 39618643, 2024). "It has been reported that, under experimental infections, HAPTO increases rapidly and remains elevated for 10–15 days, whereas CRP shows a fast increase and declines after 4–5 days." (PMID 38951921, 2024). "Regarding other infection indicators, the specificity of serum amyloid (SAA) in the early stages of infection was notably higher than that of C-reactive protein and procalcitonin." (PMID 38178046, 2024). "C-reactive protein (CRP) and white blood cell (WBC) levels are determined as inflammatory markers to detect inflammation and even infection after total shoulder arthroplasty (TSA)." (PMID 39512731, 2024). "C-reactive protein (CRP) and PCT were significantly higher than the normal range in the BSI group, indicative of the infection status of the patients." (PMID 39621250, 2024). "For infections, biomarkers such as CRP, PCT, and WBC are often used to assess the presence and severity of infection." (PMID 39441193, 2024). "C-reactive protein (CRP) is another biomarker that dramatically increases from injury, infection, and inflammation." (PMID 38684973, 2024). "For the prediction of infection, the AUC/ROC of MDW (0.84) was nearly overlapping that of procalcitonin (0.83), and C-reactive protein (0.89)." (PMID 38956252, 2024). "However, factors such as CRP, PCT, WBC, neutrophil percentage, CD4+ T cell levels, age, gender, mNGS diagnostic outcomes, infection status, mixed infection, and whether the herpes virus did not reveal significant differences between the Improvement group and the Death group (P > 0.05)." (PMID 38902783, 2024). "Post-cardiac surgery, PSP daily dosing (48.1 ng/mL—AUROC 0.76–95%CI 0.62–0.88) was shown to perform better than CRP (AUROC 0.53) and leucocytes (AUROC 0.64) in predicting infection." (PMID 39200255, 2024). "C-reactive protein (CRP) is a key marker of inflammation and can increase up to 1000-fold at sites of infection or inflammation." (PMID 38920587, 2024). "From the seventh day (October 19), the patient’s body temperature increased again and continued, C-reactive protein, interleukin-6, and procalcitonin continued to rise, and WBC continued to decrease, indicating an aggravation of infection." (PMID 39093790, 2024).
infection (continued). "C-reactive protein (CRP) is a protein of the acute phase of inflammation, the concentration of which increases thousands of times at sites of infection or inflammation." (PMID 39001884, 2024). "To assess the efficacy of inflammatory markers for early infection diagnosis in CAR-T therapy patients, we measured serum inflammatory indicators (PCT, IL-6, and CRP) at the onset of fever following CTI." (PMID 38956649, 2024). "The elevated CRP of 15 mg/L suggests inflammation, while the slightly elevated WBC of 11.4 × 10^9/L indicates a possible ongoing infection or inflammatory response." (PMID 39310523, 2024). "This novel method proved superior to CRP and PCT in distinguishing between microbiologically confirmed bacterial (n = 193) and viral (n = 291) infections." (PMID 39441193, 2024). "She then was seen by internal medicine, who took note of her worsening knee pain and ordered labs, revealing that the patient potentially had an infection based on her ESR, CRP, A/G ratio, and platelet count." (PMID 39310383, 2024). "Signs of infection were observed in blood tests: white blood cell (WBC) 13,080/μL, erythrocyte sedimentation rate (ESR) 120 mm/hour, C-reactive protein (CRP) 5.33 mg/dL." (PMID 38172867, 2024). "However, CRP may not be suitable for the diagnosis of low-virulence pathogens, since in many cases these infections are associated with low CRP levels." (PMID 39203582, 2024). "It was found that the levels of WBC count, CRP, and PCT in the intracranial infection group were higher than those in the non-infection group, with a statistical difference (P< 0.05)." (PMID 39611102, 2024). "The predictive value of CRP and PCT for infection is poor within 72 h after hospital admission but seems good after the first 72 h." (PMID 38279274, 2024). "This study aimed to assess the analytical performance of the LumiraDx CRP Test, a microfluidic immunoassay for use in POC settings, when compared to a reference method, in patients with symptoms of infection, tissue injury or inflammatory disorders." (PMID 38188655, 2024). "The systemic inflammation marker CRP and eosinophil percentage (EOS%) were greater in patients with HPV + infection, and the neutrophilic granulocyte percentage (NEUT%) was greater in patients with CC than in their respective controls." (PMID 38685022, 2024). "The evaluation will include QRS duration, levels of NT-proBNP, C-reactive protein (CRP), antibiotic therapy used, LVEF, LVESV, LVEDV, HFH, postoperative infection rate, 6 min walking test, pacing threshold, and mortality." (PMID 39457668, 2024). "FebriDx is a single-use, analyser-free, point-of-care test with markers for bacterial (C-reactive protein [CRP]) and viral (myxovirus resistance protein A [MxA]) infection, measured on a finger-prick blood sample." (PMID 38688532, 2024). "As infection is the most common trigger for T2MI, C reactive protein (CRP), a marker of acute inflammatory/infective state, has been evaluated as a potential diagnostic tool." (PMID 39457985, 2024). "Although both CRP and ESR levels are typically elevated following spinal surgery or infection, CRP returns to baseline more quickly after timely treatment or surgical intervention, in comparison to ESR." (PMID 38173524, 2024). "We then performed an unpaired t-test using the standard deviation and the average values of P-SEP, CRP, PCT, WBC count, and neutrophil count of patients with infections of bacterial versus viral origin." (PMID 38790589, 2024). "Only one patient (2.70%) sustained medical complications within 30 days postoperatively, experiencing a sudden rise in c-reactive protein (CRP) during the 5th postoperative day, provoked by a local infection managed with antibiotic regimen administration." (PMID 38337513, 2024). "Inflammatory markers, such as C-reactive protein (CRP), interleukin-6 (IL-6), and tumour necrosis factor-α (TNF-α), have been shown to increase dramatically in response to infection, tissue damage, and active disease." (PMID 38956273, 2024).
infection (continued). "The C-reactive Protein (CRP), procalcitonin (PCT), and white blood cell count (WBC) were monitored to follow the dynamics of the infection." (PMID 38811482, 2024). "In the context of infection after THA, the CRP value becomes particularly significant for acute infection." (PMID 39120214, 2024). "Recently, WBC, CRP, and PCT have been widely used to diagnose postoperative infection problems in clinical practice." (PMID 38504206, 2024). "Within our study, 16.1% of cases exhibited infections after ERCP, defined by the presence of fever and an increase in CRP levels leading to antibiotic therapy." (PMID 38592264, 2024). "C-reactive protein (CRP) serves as an inflammatory marker, characterized by a rapid increase in plasma concentration during infection or tissue damage." (PMID 40046178, 2024). "It is reported that two members of which (SAA1 and SAA2) are (along with CRP) the most prominent members of the acute phase response (APR) during which their serum levels rise dramatically after trauma, infection and other stimulation." (PMID 38243232, 2024). "Elevated levels of BUN, CRP, and PCT indicate a more severe infection and inflammatory response, possibly pointing to multi-organ dysfunction syndrome, which is associated with a poorer prognosis." (PMID 39533637, 2024). "During infection, toxicity, and irritation conditions, there are high concentrations of inflammatory factors in serum, such as IL-6, IL-8, TNF, C-reactive protein (CRP), soluble glycoprotein 130 (SGP130, involved in IL-6 signal transduction, sCD30, and MCP-1)." (PMID 38415245, 2024). "Elevated CRP and PCT levels can indicate the presence of infection and help assess the response to treatment." (PMID 39202627, 2024). "While, the top 6 weighting factors for infection identified by the SVM in ML were Th%, RBC, T, LOS, white blood cell count (WBC), and CRP." (PMID 38649391, 2024). "It is worth noting that although physicians typically used CRP to assess the severity of infection, the serum level of SAA in this study was significantly higher than the serum level of CRP." (PMID 38902401, 2024). "Secondly, infection markers, including WBC, N-to-L ratios, and CRP, were added and analyzed in an integrated manner along with sICs and CK." (PMID 39654974, 2024). "The reason for prescription was present in the patient file for the treatment of 239 (92.3%), but only 105 (40.5%) prescriptions were based on an elevated biomarker of infection (WBC, CRP)." (PMID 39596727, 2024). "Serum levels increase rapidly in the first 2 h from an infectious insult, reaching a peak blood concentration at 3 h, earlier than either CRP or PCT (which peak at around 6 h and 4 h from infection, respectively)." (PMID 38790589, 2024). "According to clinical experiences, CRP, PCT, and IL-6 showed rapid increase in the early stage of infection." (PMID 39039507, 2024). "Serum C-reactive protein (CRP) is a hepatic acute-phase reactant that functions as an early marker for inflammation and infection." (PMID 38988811, 2024). "The efficacy of IL-6 detection for the early diagnosis of wound infection was proposed, considering the ability of IL-6 to activate C-reactive protein (CRP), a well-known biomarker for evaluating infection status." (PMID 39064129, 2024). "IL-6 and C reactive protein (CRP) are called aging-related “geriatric” cytokines, which increase with aging and are produced by trauma, stress, and infection, and have many physiological effects." (PMID 38256036, 2024). "C-reactive protein (CRP) and erythrocyte sedimentation rate (ESR) are commonly used inflammatory indicators for diagnosing infection." (PMID 38834591, 2024). "They found that cytokines, both in isolation and combination, were more effective in detecting infection than ESR and CRP in diagnosing prosthetic shoulder infections." (PMID 39411639, 2024). "Host-response biomarkers, predominantly C-reactive protein (CRP) and procalcitonin (PCT), have been applied to these infections." (PMID 39020244, 2024).